STAT3 (signal transducer and activator of transcription 3)
Diseases named in the same sentence as STAT3 in open-access papers (continued):
Sharing a sentence is not in itself a finding about the gene and the disease.
non-small cell lung carcinoma (continued). "Systemic administration of AZD9150 to immunodeficient mice harboring lymphoma, neuroblastoma, or non-small-cell lung cancer xenografts resulted in decreased STAT3 expression in tumor cells and reduction of tumor initiating potential following serial implantation of the AZD9150-treated tumors." (PMID 31671769, 2019). "Previous studies found that by suppressing STAT3 and p-STAT3 expression in non-small cell lung cancer cell lines, Huaier could inhibit the proliferation and the invasion of tumor." (PMID 31391034, 2019). "On the relationship between breast tumor and STAT3/p-STAT3 expression, the overexpression of STAT3 and p-STAT3 also exerts a similar effect on non-small-cell lung cancer and digestive system cancer in poorly differentiated, advanced stage, lymph node metastasis." (PMID 29560131, 2018). "Similarly in non-small cell lung cancer, STAT3 and BDNF signalling have been shown to cooperatively activate proliferative signalling." (PMID 29339786, 2018). "In addition, studies in head and neck and non-small cell lung cancer cells have shown reactivation of Stat3 signaling in the presence of dasatinib, indicating that these cancers have become resistant to dasatinib by finding a way to sustain Stat3 signaling." (PMID 26625308, 2015). "High Src activity was found to correlate with high levels of the Src effector, Signal Transducer and Activator of Transcription-3 (Stat3) in its tyrosine-705 phosphorylated, i.e., transcriptionally activated form, in the majority of Non-Small Cell Lung Cancer lines examined." (PMID 24670366, 2014). "Finally, among genes involved in cGVHD susceptibility identified in previous SNP association studies it is notable that CCR6 can induce phosphorylation of STAT3 in asthma and that STAT3 is an important binding partner of FGDR1 in the development of non-small cell lung cancer." (PMID 37731134, 2023). "Furthermore, the upregulation of VEGF mediated by the activation of JAK2/STAT3 signaling pathway has been demonstrated in non-small-cell lung cancer and other tumor cells, indicating that a similar correlation may also exist in mtLE subpopulation." (PMID 36620436, 2022). "More recently, it has been shown that IL-17 activates STAT3 in non-small cell lung carcinomas (NSCLC) cells and that treatment of HUVECs with IL-17 in vitro promoted the formation of vessel-like tubes in a dose-dependent manner." (PMID 29675018, 2018). "Since the activation of signal transducer and activator of transcription 3 (STAT3) is often deregulated in non-small cell lung carcinoma (NSCLC) cells and tissue specimens, its negative regulation can form the basis for identification of targeted therapy." (PMID 30413072, 2018). "STAT3 and TrkB activity may contribute to non-small-cell lung cancer cell proliferation." (PMID 27456333, 2016). "In non-small cell lung cancer (NSCLC), FXR acts as a tumor-promoting driver, transactivating IL-6 and IL-6ST and activating the Jak2/signal transducer and activator of transcription 3 (STAT3) pathway, thereby enhancing metastatic potential and poor prognosis." (PMID 41339918, 2025). "For example, in non-small cell lung cancer (NSCLC) patients, NK cells were found to have notably reduced miR-130a levels and concomitantly elevated STAT3 activity." (PMID 40647470, 2025). "In non-small cell lung cancer, EZF has been reported to inhibit tumor proliferation via the JAK/STAT3 pathway." (PMID 40533866, 2025). "According to findings of other studies, IL-6 produced by TAM promoted the occurrence of hepatic cancer through STAT3 signaling pathway, while IL-10 produced by TAM promoted the occurrence of non-small cell lung cancer through STATI pathway." (PMID 38244580, 2024). "In non-small-cell lung cancer cells, inhibition of the CDK9/signal transducer and activator of transcription 3 (STAT3) signaling pathway suppresses the expression of STAT3 target genes, including VEGF, thereby inhibiting tumor growth." (PMID 39519130, 2024).
non-small cell lung carcinoma (continued). "IL-17A also stimulates the production of VEGF by cancer cells via the STAT3/GIV signaling pathway, promoting angiogenesis in non-small-cell lung cancer." (PMID 39906741, 2024). "In non-small-cell lung cancer (NSCLC), SNHG3 activation by E2F1 drives proliferation and migration via the TGF-β and IL-6/JAK2/STAT3 pathways, underscoring its therapeutic relevance." (PMID 39349640, 2024). "It was reported that activation of the IGF1R/STAT3 pathway resulted in the upregulation of ALDH1, which in turn enhanced the stemness and radioresistance of non-small cell lung cancer." (PMID 39394189, 2024). "In non-small-cell lung cancer, USP28 appears to mediate STAT3 signaling through deubiquitination and stabilization." (PMID 39076972, 2024). "KLF4 also inhibits the tumor proliferation and metastasis of non-small cell lung cancer (NSCLC) through downregulating cyclin D1, upregulating p21, and inhibiting MSI2: an activator of the JAK/STAT3 signaling pathway that promotes metastasis." (PMID 37760529, 2023). "Signal transducer and activator of transcription 3 (STAT3) plays a critical role in the development and progression of non-small cell lung cancer (NSCLC) tumors." (PMID 36672335, 2023). "Studies have shown that upregulation of IL-6 activates STAT3, thereby inhibiting CD8 T-cell infiltration in non-small cell lung cancer and pancreatic cancer." (PMID 36245983, 2022). "In a mouse model of carcinogen-induced Non-Small Cell Lung Cancer (NSCLC), epithelial cell-specific knockout of Stat3 led to downregulation of MHC I on transformed epithelial cells." (PMID 35865518, 2022). "In non-small cell lung cancer, LINC81507 acts as the sponge of miR-199b-5p and exerts effects through the Caveolin1/signal transducer and activator of transcription-3 (CAV1/STAT3) signaling pathway." (PMID 34760707, 2021). "LIF-JAK/STAT3 is a recognised signalling pathway for PDAC, CRC, ovarian cancer and non-small lung cell cancer (NSCLC)." (PMID 33630157, 2021). "In non-small cell lung cancer cells, it was observed that lupeol inhibits the phosphorylation of EGFR by binding to its tyrosine kinase domain and reducing STAT3 phosphorylation, which contributes to the induction of apoptosis." (PMID 32571387, 2020). "Yu and colleagues suggested that STAT3 upregulated the expression of various target genes (Bcl-2, cyclin D1, c-myc) through a miR-197/CKS1B/STAT3 axis, which conferred chemoresistance to non-small-cell lung cancer." (PMID 32872659, 2020). "miR-320a also regulates non-small-cell lung cancer metastasis and invasion via the PI3K/Akt pathway and suppresses lung adenocarcinoma cell proliferation and metastasis by targeting STAT3 signal." (PMID 32076458, 2020). "Recently, enhanced STAT3 activation was found in an EGFR-driven, patient-derived xenograft model of non-small cell lung cancer, contributing to acquired EGFR resistance." (PMID 31422383, 2019). "STAT3 suppression decreases PD-L1 expression in ALK-positive anaplastic large cell lymphoma (ALCL) and KRAS-mutant non-small cell lung cancer (NSCLC) cells." (PMID 31835799, 2019). "Inhibiting JAK2 and STAT3 expression both suppressed STAT3 activation and reduced the expression of VEGF and bFGF in non-small-cell lung cancer (NSCLC)." (PMID 28978186, 2017). "In gefitinib-resistant non-small-cell lung cancer, IL-6R/JAK1/STAT3 signaling activation leads to de novo resistance to irreversible EGFR inhibitors." (PMID 27861147, 2017). "Here, we summarise our recent findings on the effect of the Src/Stat3 axis upon GJIC in cells transformed in culture and in lines established from Non-Small Cell Lung Cancer (NSCLC) tumors." (PMID 24670366, 2014). "We found that disruption of GSK3β activity was essential for xanthatin to exert its anticancer properties in non-small cell lung cancer (NSCLC), concurrent with preferable suppression of constitutive activation of STAT3." (PMID 24312384, 2013).
non-small cell lung carcinoma (continued). "Previously, we showed that Src promotes cancer cell survival in conjunction with STAT3 in head and neck squamous cell carcinoma (HNSCC) and non-small cell lung carcinoma (NSCLC) cells." (PMID 21776389, 2011). "Most interestingly, while using primary tumour material, we observed that in contrast to non-small-cell lung cancer samples from primary tumour tissues, all analysed samples from SCLC were strongly positive for tyrosine-phosphorylated STAT3." (PMID 19455144, 2009). "As such, it is a simple aromatic aldehyde, and it has been shown in vitro to suppress multiple oncogenic signaling pathways, including PI3K/Akt/mTOR, NF-κB, STAT3, and ERK, by disrupting the 14-3-3-mediated protein interactions in pancreatic (BxPC-3) and non-small-cell lung cancer (A549) cell lines." (PMID 40940853, 2025). "Here, using a DNA barcoding approach, the authors demonstrate EGFR TKI treatment in non-small cell lung cancer enriches for resistant subpopulation which can be prevented by treatment with the multikinase inhibitor sorafenib via inhibition of MKNK, STAT3 and MCL1." (PMID 40846697, 2025). "In non-small cell lung cancer, a novel 4′-brominated derivative of fisetin inhibits the EGFR/ERK1/2/STAT3 pathways and causes cell cycle arrest and apoptosis without having any negative effects on mice." (PMID 40728967, 2025). "JAK3 and STAT3 genes had been reported to be different among the NPC cell lines, and in other types of cancer including natural killer T cell lymphoma, and non-small cell lung cancer." (PMID 39769218, 2024). "A previous study by our laboratory demonstrated that DYRK1A could regulate STAT3/EGFR/MET signalling and sensitize EGFR wild-type non-small cell lung cancer (NSCLC) cells to AZD9291, thus indicating that DYRK1A could regulate EGFR via STAT3." (PMID 35655269, 2022). "Acting as a specific inhibitor of AKR1C1, ALA selectively inhibits the activity of AKR1C1 and ALA treatment in human non-small-cell lung cancer (NSCLC) cell results in a reduction in cell proliferation and metastasis, inhibition of AKR1C1 expression, and deactivation of STAT3." (PMID 35370661, 2022). "In addition, signal transducer and activator of transcription 3 (STAT3) was confirmed to activate CCDC66 transcription and increase the expression of circCCDC66 in non-small cell lung cancer cells." (PMID 36698408, 2022). "Upregulated STAT3 has been shown to promote EMT in non-small-cell lung cancer, therefore, it is speculated that DHX9 mediates EMT via STAT3 regulation in lung adenocarcinoma." (PMID 33437516, 2020). "DDIAS depletion attenuated IL-6–induced STAT3 phosphorylation at Y705 but not at S727 in non-small cell lung cancer (NSCLC) cells, such as NCI-H23 and NCI-H1703." (PMID 31900385, 2020). "It has been reported to promote non-small cell lung cancer (NSCLC) progression and metastasis by initiating forward feedback loop between PAFR and STAT3, and contributes to the malignant development of esophageal squamous cell carcinoma by stimulating PI3K/AKT activation." (PMID 28099922, 2017). "However, comparatively few studies have explored the therapeutic efficacy of YSY01A in non-small cell lung carcinoma and little is known about the mechanism by which YSY01A modulates STAT3 signaling cascade." (PMID 28883791, 2017). "Here, we identify a miR-197/CKS1B/STAT3-mediated PD-L1 network in chemoresistant non-small-cell lung cancer (NSCLC), independent of immunoinhibitory signals." (PMID 25597412, 2015). "Moreover, the USP28 substrate STAT3 participates in the drug resistance of cancer therapy, suggesting that USP28 may play an essential role in therapy resistance in non-small cell lung cancer." (PMID 36879346, 2023). "UA exhibited a strong apoptotic activity against non-small cell lung cancer; it dow-regulated the expression of the JAK2/STAT3 pathway and reduced the expression of VEGF and PDL-1, hence hampering the STAT3/PD-L1 complex formation and the EGFR/JAFK2/STAT3 signaling pathways." (PMID 35887090, 2022).
non-small cell lung carcinoma (continued). "In addition, phosphorylation of STAT3 decreased after knockdown and expression of the anti-apoptotic protein BCL-2 decreased, while the expression of the pro-apoptotic protein, Bax, increased, which aligns with their previous research in non-small-cell lung carcinoma." (PMID 41148789, 2025). "Additionally, AHR drives non-small cell lung cancer tumorigenesis when the AHR protein is stabilized after deubiquitination by ubiquitin carboxy-terminal hydrolase isozyme L3, and this AHR action of cancer tumorigenesis may involve Jak2/STAT3 signaling." (PMID 37894798, 2023). "In the present report, we noticed that OP-D can modulate STAT3 activation and abrogate tumor growth in a preclinical non-small cell lung carcinoma (NSCLC) model." (PMID 30413072, 2018). "Constitutive activation of STAT3 is a common feature in many solid tumors including non-small cell lung carcinoma (NSCLC)." (PMID 22319590, 2012). "Paradoxically, we find that YSY01A abrogates constitutive activation of STAT3 via proteasome-independent degradation of gp130 and JAK2, but not transcriptional regulation, in human A549 non-small cell lung cancer cells." (PMID 28883791, 2017).
lymphoma (263 papers, 2007 to 2026). A malignant (clonal) proliferation of B- lymphocytes or T- lymphocytes which involves the lymph nodes, bone marrow and/or extranodal sites. "In lymphoma‐associated macrophages, STAT3 regulates the expression of immune checkpoint proteins, including programmed death‐1 (PD‐1) and programmed death‐ligand 1 (PD‐L1), contributing to immune evasion in cancer." (PMID 40166646, 2025). "The STAT3 -associated gene signature shared similarities to the HIV-associated lymphomas with similar integration sites." (PMID 40236153, 2025). "The provirus had only a 3′ LTR sequence with more vigorous promoter activity than the STAT3 promoter, and lymphoma cells showed high levels of STAT3, suggesting that the up-regulation of STAT3 caused by HIV-1 integration can induce B-cell lymphoma." (PMID 40244051, 2025). "Recently, gain-of-function mutations in STAT5B and STAT3 have been found in patients with various types of leukemia and lymphomas." (PMID 36765714, 2023). "As JAK–STAT and NF‐κB pathways were involved in lymphoma, we first found that the rs744166 of STAT3 and rs6503691 of STAT5B contributed to lymphoma susceptibility under codominant, recessive, codominant, and allele models (all p < 0.05)." (PMID 37329186, 2023). "Increased levels of IL-6, the major upstream cytokine to activate STAT3, are also associated with a poor lymphoma prognosis." (PMID 37686472, 2023). "Our analyses in PBL subcohorts further showed that STAT3 mutations predominantly occur in HIV-associated PBLs as these lymphomas harbored significantly more frequently STAT3 mutations compared to other PBL subtypes." (PMID 34465776, 2021). "Some studies on ALK-mutated lymphomas have shown that ALK rearrangements lead to increased STAT3 signal transduction, which is involved in downstream signaling of inflammatory cytokines." (PMID 33996610, 2021). "In conclusion, the activation of STAT3 has been strongly implicated in the pathogenesis of NPM-ALK(+) lymphoma." (PMID 33466277, 2021). "More recently, gain-of-function (GOF) mutations in STAT5B and STAT3 have been found in patients with leukemias and lymphomas." (PMID 31963765, 2020). "Of note, STAT3/STAT5B mutations were absent in all non-LGL T-CLPD patients, except for an adult T-cell leukemia/lymphoma case that showed the STAT3-S614R mutation." (PMID 33255665, 2020). "Subsequently, several types of solid tumors, leukemia, and lymphomas have been linked with constitutive activation of STAT3." (PMID 30847297, 2019). "IL-6–induced STAT3 or STAT5 activation is a critical mechanism underlying PI3K inhibitor resistance in lymphoma, supporting the utility of IL-6 as an effective biomarker to predict therapeutic response to PI3K inhibitors." (PMID 31601188, 2019). "Positive hits were further validated in different models including STAT3 mutation-containing Ba/F3 cells, NK cell leukemia/lymphoma cells and LGL leukemia patient samples." (PMID 29228628, 2017). "Specifically, STAT3 inhibition also serves as a possible therapeutic target for lymphomas with the SQSTM1-ALK variant translocation." (PMID 28665943, 2017). "Because of auto-secretion of cytokines by the lymphoma cells, it should be possible to activate expressed variant STAT3 and thus replace activation of endogenous STAT3s." (PMID 26727576, 2016). "Intrigued by our predictive and experimental data linking Bcl-2 overexpression to STAT3 activation, we set out to investigate the clinical relevance of this association in primary cells derived from patients with lymphomas." (PMID 26430964, 2015). "Upon transplantation into NK cell-deficient mice differences in lymphoma size were abolished indicating that STAT3 expression in the tumor cells controls NK cell-dependent tumor surveillance." (PMID 24473086, 2014). "We have previously demonstrated that JAK2 mutations are not the cause; however, there have been few reports on the role of STAT3 mutations in lymphoma in general and specifically DLBCL." (PMID 23861822, 2013).